GBP6 (guanylate binding protein family member 6)
Description:
Interferon (IFN)-inducible GTPase that plays important roles in innate immunity against a diverse range of bacterial, viral and protozoan pathogens, such as bacterial pathogens Listeria monocytogenes and Mycobacterium bovis BCG as well as the protozoan pathogen Toxoplasma gondii (By similarity). Confers protection to several pathogens, including the bacterial pathogens Listeria monocytogenes and Mycobacterium bovis BCG as well as the protozoan pathogen Toxoplasma gondii (By similarity).
Synonyms: DKFZp686G0786
Tractability: PROTAC: UniProt records ubiquitination sites on it.
Gene: Protein-coding gene on chromosome 1 (89,363,895 to 89,388,160, forward strand). Ensembl gene ENSG00000183347.
Subcellular location: Cytoplasmic vesicle
Pathways (Reactome):
Disease: Enterobacterial factors antagonize host defense
Immune System: Interferon gamma signaling
Gene Ontology:
Molecular function: protein binding; GTP binding; GTPase activity
Biological process: cellular response to type II interferon; defense response to bacterium; defense response to Gram-positive bacterium; defense response to protozoan; immune response
Cellular component: extracellular exosome; cytoplasmic vesicle; cytosol
Genetic constraint (gnomAD): Loss-of-function variants: 52 observed, 62.32 expected, observed/expected ratio (o/e) 0.83, 90% interval 0.67 to 1.05. The upper end of that interval is the gene's LOEUF score, 1.05, which puts it in group 4 of 6, group 1 being the genes least tolerant of losing a copy. Missense variants: 744 observed, 786.79 expected, observed/expected ratio (o/e) 0.95, 90% interval 0.89 to 1. Synonymous variants: 254 observed, 288.02 expected, observed/expected ratio (o/e) 0.88, 90% interval 0.8 to 0.98.
Homologues: Orthologues: chimpanzee GBP6 (99% identical), macaque GBP6 (93% identical), dog GBP6 (73% identical), mouse Gbp11 (67% identical), mouse Gbp6 (67% identical), mouse Gbp10 (66% identical), mouse Gbp9 (66% identical), rat Gbp6 (65% identical), mouse Gbp4 (63% identical), rat Gbp6-ps1 (58% identical), mouse Gbp8 (58% identical), tropical clawed frog gbp6 (44% identical), and 1 more. Paralogues in human: GBP4 (69% identical), GBP7 (69% identical), GBP2 (49% identical), GBP1 (49% identical), GBP3 (48% identical), GBP5 (46% identical), ATL2 (18% identical), ATL1 (18% identical), ATL3 (18% identical), RNF112 (13% identical).
Diseases named in the same sentence as GBP6 in open-access papers:
GBP6 is named in the same sentence as 32 diseases in open-access papers, as found by Europe PMC text mining. Sharing a sentence is not in itself a finding about the gene and the disease. The quoted sentences say what the papers report.
tongue squamous cell carcinoma (3 papers, 2021 to 2025). A squamous cell carcinoma that arises from the tongue. "Low GBP6 expression was correlated with poor cell differentiation and lymph node metastasis in tongue squamous cell carcinoma (TSCC), and low GBP7 expression was linked with short OS in HNSC patients." (PMID 35222540, 2022). "GBP6 has been confirmed to have a poor prognosis in tongue squamous cell carcinoma (TSCC) patients due to its low expression in TSCC." (PMID 34714841, 2021).
atherosclerosis (2 papers, 2018). A disease characterized by the build-up of fatty material and calcium deposition in the arterial wall resulting in partial or complete occlusion of the arterial lumen. "In mice, elevated levels of Gbp3 and Gbp6 were linked with the pathogenesis of atherosclerosis." (PMID 29467757, 2018). "Following a Western-type diet GBP3 and GBP6 expression levels increase during foam cell formation in mice, indirectly suggesting their role in the acceleration of atherosclerosis by hypercholesterolemia." (PMID 30303482, 2018). "Coupled with evidence from our network-based prioritization, this suggests that other members of the GBP family with similar expression patterns to GBP3 and GBP6, including the top-prioritized GBP1, might also play a role in atherosclerosis mediated by hypercholesterolemia." (PMID 30303482, 2018).
diabetes (2 papers, 2020 to 2022). "GBP6 is reported in diabetes but is not reported in PC patients with diabetes." (PMID 33240632, 2020).
dilated cardiomyopathy (2 papers, 2022 to 2025). Cardiomyopathy which is characterized by dilation and contractile dysfunction of the left and right ventricles. "GBP5 and GBP6 were increased in cardiomyocytes of ICI-associated myocarditis (ICIM) patients compared to patients with dilated cardiomyopathy and virus-induced myocarditis." (PMID 35222540, 2022). "In particular, GBP5 and GBP6 were elevated in these samples compared to viral myocarditis, and absent in biopsies from patients with dilated cardiomyopathy." (PMID 40940808, 2025).
liver cancer (2 papers, 2021 to 2023). An epithelial or non-epithelial malignant neoplasm that arises from the liver. "We found that 6 mRNA expressions were significantly different (P<0.05), including GBP6 (guanylate binding protein), TMEM (transmembrane protein), CTCFL (liver cancer marker gene), KRT5 (keratin 5), LY6D (lymphocyte antigen) and TMEM179 (transmembrane protein)." (PMID 34714841, 2021). "The single‐cell data also revealed that GBP6 was not expressed in the liver and the expression of GBP7 in liver cancer immune cells was extremely low." (PMID 37551111, 2023).
adenoma (1 paper, 2017). A neoplasm arising from the epithelium. "Analysis of microdissected dysplastic epithelium also revealed possible roles for cancer-related genes not previously associated with CRC (GBP6, PLXND1) in early stage adenoma progression." (PMID 28747659, 2017).
gastric cancer (1 paper, 2021). A primary or metastatic malignant neoplasm involving the stomach. "In gastric cancer, levels of GBP6 methylation are negatively correlated with their mRNA expression." (PMID 34796198, 2021).
gingivitis (1 paper, 2025). A disorder involving inflammation of the gums; may affect surrounding and supporting structures of the teeth. "The proteins CD55, GBP6, IGHV3-35, and IGKV1-6 are significant markers in the context of the host response to bacterial infections, particularly in relation to gingivitis and treatment outcomes." (PMID 41156831, 2025).
head and neck squamous cell carcinoma (1 paper, 2025). A squamous cell carcinoma that arises from any of the following anatomic sites: lip and oral cavity, nasal cavity, paranasal sinuses, pharynx, larynx, and salivary glands. "Meanwhile, low expression of GBP6/7 levels in head and neck squamous cell carcinoma (HNSCC) correlates with shorter survival, indicating possible tumor-suppressing activity in specific contexts, while its cytoplasmic vesicle localization hints at roles in immune regulation or vesicular trafficking." (PMID 40564939, 2025).
leukemia (1 paper, 2021). A malignant (clonal) hematologic disorder, involving hematopoietic stem cells and characterized by the presence of primitive or atypical myeloid or lymphoid cells in the bone marrow and the blood. "In this study, we revealed that GBP1–5 are significantly downregulated in AML, ALL, or CLL patients compared with the non-leukemic population, and elevated levels of GBP1, GBP3, GBP4, and GBP6 are associated with prolonged survival time in leukemia and lymphoma patients." (PMID 34294680, 2021). "GBP1, GBP3, GBP4, and GBP6 were beneficial for overall survival, indicating that GBPs are favorable prognosis markers for tested leukemia and lymphoma types." (PMID 34294680, 2021). "The comparable mRNA levels of most GBP genes, (GBP1–5), except for GBP6, were significantly downregulated in the three types of leukemia." (PMID 34294680, 2021).
oral cancer (1 paper, 2021). "Also, GBP6 is associated with oral cancer and HNSC therefore can be used as a prognostic marker." (PMID 34796198, 2021).
oral squamous cell carcinoma (1 paper, 2025). "GBP6’s reduction in oral squamous cell carcinoma and tongue squamous cell carcinoma hints at diagnostic potential, measurable in saliva, tissue biopsies, or circulating DNA via qPCR, RNA sequencing, or liquid biopsies, pending larger cohort confirmation." (PMID 40564939, 2025). "GBP6 exhibits reduced expression in oral squamous cell carcinoma, suggesting potential as a diagnostic marker, though findings are limited by small sample sizes." (PMID 40564939, 2025).
psoriasis (1 paper, 2023). An autoimmune condition characterized by red, well-delineated plaques with silvery scales that are usually on the extensor surfaces and scalp. "Other psoriasis-linked genes include APOE, CTLA4, DEFB4, GBP6, LCE, MCP1, VDR, and ZNF313." (PMID 37569685, 2023).
Sepsis (1 paper, 2022). Sepsis is defined as life-threatening organ dysfunction caused by a dysregulated host response to infection. "The gene expression of GBP2, GBP6, and GBP7 in the Sham group was significantly higher than that in the sepsis group." (PMID 36405762, 2022).
squamous cell carcinoma (1 paper, 2024). A carcinoma arising from squamous epithelial cells. "For example, GBP6 showed down-regulation and slow reversibility in the clinic group and is known to be associated with reduced overall survival in squamous cell carcinoma of the head and neck." (PMID 38589970, 2024).
infection (9 papers, 2014 to 2025). The state of being infected such as from the introduction of a foreign agent such as serum, vaccine, antigenic substance or organism. "In summary, this study identifies IRF1 and GBP6 as 2 key loci at which infection-induced systemic inflammation leads to epigenetic changes that are conserved from HSPCs to downstream monocytes, providing a mechanistic avenue for central trained immunity." (PMID 41364527, 2025). "After STM infection migratory ILCs express significantly higher levels of Ccl3, Gbp2, Gbp6, Irf1, Irf4, Irf7, Pml and Stat1, all of which are regulated in response to interferon gamma." (PMID 33414524, 2021). "Interestingly, another Gbp gene cluster (Gbp4/Gbp6/Gbp9) remained in the B compartment before and after infection, but their compartment values increased post-infection." (PMID 40539063, 2025). "The other gene in the same GWAS region, GBP6, showed strong evidence of ASE (p < 0.01) at all time-points post infection." (PMID 28393889, 2017). "Transcriptomic profiling of MPXV-infected MK2 cells at 7 h post-infection further revealed the upregulation of multiple guanylate-binding protein (GBP) family members, including GBP3, GBP5, GBP6, and GBP7, highlighting a broader antiviral gene program downstream of type I IFN–IRF1 signaling." (PMID 41225161, 2025). "Finally, heightened induction of Gbp2, Gbp4, Gbp5, Gbp6, and Ip10 in Sts−/− cells relative to wild type cells was observed following both IFNγ treatment alone and LVS infection of IFNγ‐treated cells." (PMID 32841534, 2020). "In addition, six genes (SLFN12, MX2, TRIM30A, GBP1, GBP6, and IFIH1) were common to 15 dpi and the early infection period." (PMID 29147886, 2018).
cancer (6 papers, 2012 to 2026). A tumor composed of atypical neoplastic, often pleomorphic cells that invade other tissues. "Multivariate analysis suggested that N-stage (HR = 1.33, 95% CI: 1.03–1.72, P < 0.05), high expressions of GBP1 and low expression of GBP6/7 were linked to shorter OS of cancer patients." (PMID 32269280, 2020). "Similarly, GBP1‐5 showed strong positive associations with the Th1 cell recruiting in the cancer‐immunity cycle, while GBP6‐7 had weak correlations with this step." (PMID 37551111, 2023). "The results demonstrated that the expression of GBP1 and GBP5 were higher in HNSCC tissues, while the expression level of GBP6 was lower in cancer tissues." (PMID 32269280, 2020). "Careful inspection showed that all cancer counts and most normal counts of GBP6 were contributed by the tongue tissue source." (PMID 23282184, 2012). "By analyzing the mRNA expression of GBPs in pan-cancer, we found that GBP1-5 were highly expressed in tumor tissues, while GBP6 and GBP7 were less expressed." (PMID 36246628, 2022). "Gene set enrichment analysis (GSEA) of cancer hallmarks pathways in neutrophils showed upregulation of IFN-γ response genes in Group 1 compared with Group 2, which is confirmed by higher expression of IFN-γ–inducible guanylate binding proteins (Gbp2, Gbp4, Gbp6, and Gbp7)." (PMID 41165751, 2026).
tumor (3 papers, 2020 to 2023). "However, no expression and low protein expression of GBP6 was observed in normal and tumor tissues." (PMID 32269280, 2020).
inflammatory myopathies (1 paper, 2023). "Transcription of the guanylate-binding protein 6 (GBP6) gene, which is induced by IFNγ signaling, was seven times higher in sIBM compared to controls or other inflammatory myopathies." (PMID 37731843, 2023).
GBP6 also shares sentences with these, for which no sentence is quoted: viral infections (3 papers); bacterial infections (2); Hypercholesterolemia (1); influenza (1); intraepithelial neoplasia (1); lymph node metastasis (1); lymphoma (1); myocarditis (1); parasitic infection (1); rheumatic diseases (1); sarcoidosis (1); tuberculosis (1); viral myocarditis (1).